CRP (C-reactive protein)
Diseases named in the same sentence as CRP in open-access papers (continued):
Sharing a sentence is not in itself a finding about the gene and the disease.
Hypertension (continued). "Sweet cherry consumption could therefore help to reduce the risk of arthritis (indicated by CRP, TNFα, IL-18 and IL-1Ra), cardiovascular disease (CRP, ferritin, ET-1, EN-RAGE, PAI-1 and IL-18), cancer (ET-1), and hypertension (ET-1)." (PMID 28732012, 2017). "Patients with CIN had higher age, longer reperfusion times, higher prevalence of hypertension, higher glucose level on admission, higher peak creatine phosphokinase and creatine kinase MB, and higher hs‐CRP on admission than those without CIN (all P<0.05)." (PMID 28835362, 2017). "Moreover, OPG was directly correlated with SBP (p < 0.0001), hypertension duration (p = 0.0018), PTH (p < 0.0001), phosphate (p < 0.0001), CRP (p < 0.0001), and macrovascular events (p < 0.0001)." (PMID 28683789, 2017). "In contrast, in participants with existing CVE, neither the adjustment for CRP or hypertension influenced the UA effect on cardiovascular mortality or other study endpoints." (PMID 27978810, 2016). "Therefore, this study performed respiratory sleep monitoring, ambulatory blood pressure monitoring, and laboratory tests on hypertension patients to investigate the correlations between OSAHS, blood pressure fluctuations, and CRP to guide clinical treatment." (PMID 26858795, 2016). "When compared with subjects in Q1 group, those with higher homocysteine levels were more likely to be older, male, and current smokers, and they tended to have increased prevalence of hypertension as well as higher levels of BMI, ALT, TBIL, ALB, serum uric acid, TG, hs-CRP and creatinine." (PMID 27955646, 2016). "Both CRP (HR, 2.54; 95% CI, 1.26–5.12; P = 0.009) and oxLDL (HR, 2.24; 95% CI, 1.14–4.40; P = 0.019) were multivariate predictors of incident hypertension in LAF patients, but not in the controls." (PMID 26229238, 2015). "Further, in women the association between endothelin-1 levels and CHD remained significant after adjustment for age in combination with WHR, BMI, LDL-cholesterol, HDL-cholesterol, hypertension, CRP, triglycerides or medications (data not shown)." (PMID 26573599, 2015). "The CKD progressors were older, had higher systolic BP (SBP), higher prevalence rates of hypertension (92.4% vs 72.1%), more use of antihypertensive drugs, and higher triglycerides and CRP (all P < .001, vs subjects with no CKD progression)." (PMID 25166721, 2014). "We demonstrated that diuretic use vs. non-use, hypertension, higher bicarbonate, hemoglobin and CRP levels significantly correlated with hypokalemia." (PMID 23843989, 2013). "Individuals with BMI ≥ 25 kg/m2 OR = 2.28(1.13-4.6) and lower MMI OR = 13.4 (5.21-34.56) showed greater chances of high UA levels even after all adjustments (gender, age, CRP, gamma-gt, LDL, creatinine, urea, albumin, HDL-c, TG, arterial hypertension and glucose)." (PMID 23311699, 2013). "Female vs male, diuretic use vs. non-use, hypertension, higher eGFR, bicarbonate, CRP and hemoglobin levels significantly correlated with hypokalemia." (PMID 23843989, 2013). "Compared with non-DN patients, DN patients more frequently had hypertension, cardiovascular disease, and stroke, as well as presented with a higher BMI, eGFR, and CRP, but a lower DBP, MAP, and serum albumin." (PMID 23585903, 2013). "Inversely, patients without hypertension in the MAC group had higher hs-CRP levels than those patients without hypertension in the control group." (PMID 22529527, 2012). "Children classed as obese, were more likely to have high blood pressure, high cholesterol, elevated fasting glucose, raised CRP and lower adiponectin, compared to non-obese children." (PMID 22693553, 2012). "Patients from Group I toward Group IV were increasingly older, more frequently women, had higher rates of previous hypertension episodes and coronary artery disease, were above Killip class I, and exhibited increasing NT-pro BNP and high-sensitivity C-reactive protein (hs-CRP)." (PMID 22035298, 2011).
Hypertension (continued). "In addition, the use of easily obtainable and lost-cost secondary mediators (CRP, HDL-C, SBP, DBP) together with self-reported hypertension or use of anti-hypertension medication enhances the feasibility of replicating this approach in other large cohort studies." (PMID 41295355, 2025). "Additionally, the body adiposity index (BAI) showed a correlation with C-reactive protein (CRP) levels, independent of both hypertension and gender." (PMID 40943267, 2025). "LDL, CRP and hypertension also contributed, but age, sex andMHR did not." (PMID 41393495, 2025). "However, 7 pivotal factors, Cigarettes per Day, alcoholic drinks per week, BMI, hypertension, CRP, T2D and rheumatoid arthritis, were not adjusted in their analysis." (PMID 39787159, 2025). "However, individuals with a higher CRP/albuminratio tended to have a more severe DFI, a higher incidence of hypertension, andhigher WBC and platelet counts, neutrophil percentage, and fasting glucose,HbA1c, and CRP levels but lower RBC, hemoglobin, and albumin levels (P <0.05)." (PMID 40622101, 2025). "Notably, eGFR, DM, cancer, cardiovascular disease, and CRP log were baseline factors that were positively correlated with the MIS, whereas age, hypertension, hemoglobin level, albumin level, cholesterol log, phosphorus level, BMI, and muscle mass index were negatively correlated with the MIS." (PMID 39683409, 2024). "Consistent human findings demonstrate that elevated plasma levels of pro-inflammatory cytokines, including IL-6 and C-reactive protein (CRP), in middle-aged and older individuals without cardiovascular disease are associated with an increased likelihood of developing hypertension." (PMID 39595928, 2024). "Patients with low ABIs had a greater prevalence of DM(p = 0.011), elevated CRP and galectin-3 levels (both p<0.001), and lower creatinine (p = 0.012), but no significant disparitiesin gender, hypertension prevalence, smoking, blood pressure, HD vintage, or Kt/Vwere observed between groups." (PMID 39076571, 2024). "Of these, model 1 adjusted for age and sex, model 2 adjusted for age, sex, hypertension, family history, MI history, PCI/coronary artery bypass grafting (CABG) history, NYHA classification, ACS type, LDL-C, blood glucose, and hypersensitive C-reactive protein (hs-CRP)." (PMID 38242883, 2024). "While inflammatory markers such as white blood cell count, C-reactive protein and procalcitonin were elevated, the patient did not exhibit stress-induced hypertension, fever, rebound tenderness, or abdominal muscle tension, and blood microbial cultures did not yield positive results." (PMID 38200597, 2024). "In addition, the anemia group differed significantly from the non-anemia group in terms of smoking status, and alcohol consumption, social engagements, nutritional status, CRP, MCV as well as chronic disease including hypertension, dyslipidemia, CKD and chronic pain." (PMID 37553590, 2023). "In addition, age, sex, race, PIR, work status, work shift, smoking, hypertension, DM, dyslipidemia, depression, OSA, CRP, total energy intake, and VD collection season were all significantly associated with insomnia and were included in the adjustment of multivariate models (all P < 0.05)." (PMID 38170097, 2023). "Third, increased CRP might reduce nitric oxide bioavailability via decreasing urinary excretion of cyclic guanosine monophosphate and activating NADPH oxidase, which could aggravate hypertension and thus MetS." (PMID 34991636, 2022). "Compared with individuals without T2D, individuals with T2D had higher mean age, BMI, waist circumference, C-reactive protein, creatinine, total cholesterol, uric acid, and more male, Mexican American, non-Hispanic Black, former smoking, history of cancer, hypertension, CVD, and MetS at baseline." (PMID 36440190, 2022).
Hypertension (continued). "The LTL levels were significantly associated with sex, BMI, waist circumference, SBP, DBP, history of hypertension, education levels, smoking status, alcohol consumption, physical activity, TC, CRP, SUA, eGFR, and the TyG index, but not poverty to income ratio." (PMID 35721750, 2022). "We investigated the factors associated with bailout ECMO insertion, and found that advanced age (≥70 years), preadmission CS, absence of hypertension, and starting CRP within 9 min of the MI were beneficial; however, the benefits were not statistically significant." (PMID 34577809, 2021). "Overall, CD patients had similar clinical characteristics and outcomes to non-CD controls, matched by age, sex, hypertension, DM and hospital, except from a higher prevalence of atrial fibrillation and chronic heart failure, and lower C-reactive protein levels." (PMID 34645833, 2021). "The CRP test was performed in 30,418 subjects from the total population (of those, 1387 were subjects with hypertension and 29,031 were subjects without hypertension), and the mean CRP test result was 3.7 ± 10.1 mg/L, the median was 1.1 mg/L, and the mode was 0.4 mg/L." (PMID 33419028, 2021). "More recently, a multicenter study including 1128 patients with hypertension and COVID‐19 reported that the number of patients with high CRP values who had received ACEI/ARB therapy showed no significantly different than in the patients who had not received ACEI/ARB therapy." (PMID 32757246, 2020). "Furthermore, women with and without hypertension were found to have significantly higher HRs of CRP as compared with men." (PMID 30872696, 2019). "Statistically significant positive correlation was observed between serum resistin and TLC only in group D i.e. patients of myocardial infarction with hypertension (r=0.459, n=20, p=0.042) while correlation was non-significant between serum resistin and CRP in all four study groups (Table-III)." (PMID 31258568, 2019). "CRP rs1205 and rs876537 C > T variations were significantly correlated with hs-CRP, after adjusted for age, gender, BMI, TC, TG, HDL-C, LDL-C, smoking, drinking, T2DM and hypertension, the standard regression coefficients were 0.064 and 0.066, respectively, P < 0.001." (PMID 31694563, 2019). "Hypertensive disorders were not related to significant difference in CRP (p=0.182)." (PMID 32082531, 2019). "The percentage of NK cells was significantly higher in the forest group than in the urban group among subgroups of male, higher BMI (≥ 25 kg/m2), without hypertension, lower hs-CRP levels, hyperglycemia (fasting glucose ≥ 100 mg/dL), without smoking habit, and with tea drinking habit." (PMID 29662662, 2018). "While the mean BP at most CRP levels would not reach the threshold for classification as hypertension, these modest differences in SBP may also explain the known elevated risk for CVD in RA compared to the general population." (PMID 29855349, 2018). "This included lower levels of insulin, glycated hemoglobin, blood glucose, inflammatory markers (IL-6 and CRP), and hemostatic factors (von Willebrand factor, factor VIII, tPA antigen, and D-dimer); a smaller waist circumference; and higher lung function and reduced odds of hypertension." (PMID 30124747, 2018). "Indeed, in that study only the baseline levels of sVCAM-1 (but not sICAM-1, CRP, IL-6 and TNF-α) were associated with the 15 year cumulative incidence of hypertension." (PMID 29101422, 2018). "Although the increase in CRP levels in Weber B and Weber C groups was not clinically significant, we detected a trend towards systemic low-grade inflammation in the patients with hypertension who presented a reduced exercise capacity." (PMID 30291307, 2018).
Hypertension (continued). "In addition, one of the following should be fulfilled: pulse deficit or claudication, blood pressure discrepancy > 10 mm Hg in any limb, hypertension with systolic or diastolic > 95th centile for height, and erythrocyte sedimentation rate (ESR) > 20 mm/h or elevated C-reactive protein (CRP)." (PMID 27965905, 2016). "NHS initiatives are encouraging pharmacist independent prescribers in certain areas such as hypertension and respiratory illness, and it was suggested that antibiotic prescribing for LRTI, guided by a POC CRP-based algorithm, could be evaluated for inclusion in future policies." (PMID 26940107, 2016). "CRP effectively predicts future hypertension, suggesting that inflammation may precede and not just follow blood pressure elevation." (PMID 26989902, 2016). "In the Inter99 study, we have previously found that leptin, but not adiponectin or CRP, may play a mediating role in overweight-induced hypertension." (PMID 26035431, 2015). "No significant relation was observed between hs-CRP and hypertension." (PMID 25237581, 2014). "No significant relation was observed between hs-CRP and hypertension (P > 0.05)." (PMID 25237581, 2014). "By detecting a number of risk factors, it was found that age, gender, systolic blood pressure (SBP), diastolic blood pressure (DBP), fasting glucose, HbA1c, TC, LDL, HDL, TG, BMI, CRP and incidences of hypertension and hyperlipidemia were not different between one group and another (data not shown)." (PMID 24669241, 2014). "Additionally, no change in the observed results was found with adjustment for hypertension, hypertension treatment, or CRP (CRP not available in AADM or CADM)." (PMID 22973513, 2012). "The major new finding from this study is that female gender, low income, high BMI and doctor-diagnosed hypertension, all independently increased the odds of a CRP elevation being repeated rather than one-time, with the association with BMI being non-linear and different by gender." (PMID 22558327, 2012). "Therefore, regular, consistent aerobic and combined training, as well as prolonged resistance exercise, significantly reduce CRP levels in hypertensive patients, highlighting exercise's role as a non-pharmacological strategy for managing hypertension through the reduction of inflammation." (PMID 39246645, 2024). "Thus, inflammatory mediators such as C-reactive protein (CRP), tumor necrosis factor -α (TNF-α) and interleukin-6 (IL-6) may be the link between periodontitis and hypertension, and smoking may promote the co-occurrence and development of the two diseases as a common risk factor." (PMID 37308938, 2023). "The aim of this study is to assess proinflammatory status serum indicators (C-reactive protein (CRP), tumor necrosis factor alpha (TNF-α), interleukin-6 (IL-6)) in middle-aged males (M) and females (F) with essential hypertension (HTN) depending on left ventricular (LV) diastolic dysfunction (LVDD)." (PMID 35997392, 2022). "There was no group difference in CRP between self-selected and not self-selected, male or female and smoking or non-smoking Kitavans, nor between male or female and smoking or non-smoking Swedish controls and Swedish controls with or without a diagnosis of type 2 diabetes and/or hypertension." (PMID 33334321, 2020). "In our study, patients with hypertension exhibited higher levels of VLDL, triglycerides, CRP, and WBC than individuals without hypertension." (PMID 40572711, 2025). "The results consistently indicated that patients in the SCI group were more likely to be older and to have complicated hypertension, NEU, MONO, CRP, ESR, and PLT than were those in the No-SCI group, while LYM, HGB, and ALB were more common in the No-SCI group." (PMID 38565845, 2024).
Hypertension (continued). "In addition, our study also suggested that the positive correlation between CRP and kidney stones is similar across gender, BMI, hypertension, CKD and DM status, and the presence or absence of smoking or alcohol consumption, and may be applicable to different population settings." (PMID 38281018, 2024). "Compared with non-vulnerable plaques, smoking history, history of hypertension, history of renal insufficiency, HCY, CRP, SSA, fasting blood glucose, Tyg index were significantly correlated with vulnerable coronary plaques (P < .05)." (PMID 39287294, 2024). "Furthermore, the findings might not specifically apply to specific groups with CRP elevation secondary to other conditions, as we included studies where participants had high blood pressure and focused on the impact of exercise on CRP levels, regardless of their other underlying conditions." (PMID 39246645, 2024). "Compared with the non-MAFLD population, age, BMI, ALT, CRP, TC, TG, LDL, HDL, energy, the proportion of Mexican Americans, DM, and hypertension were higher in the MAFLD population, while the proportion of higher education was lower." (PMID 37305083, 2023). "The patients with arterial hypertension exhibited higher concentrations of suPAR-1, suPAR-3 and suPAR-7, as well as CRP-1, CRP-3 and CRP-7, than the patients without arterial hypertension." (PMID 35330458, 2022). "The risk curve revealed that considering the influence of different outcome time, patients with high levels of WBC, CRP, PLT, old age, and hypertension had a higher incidence of HF, and the effect of UA was not obvious enough." (PMID 35559036, 2022). "White blood cell and neutrophil counts remained higher in the hypertension group than in the nonhypertension group for almost the entire period of hospitalization; SAA and CRP continued to increase until approximately 10 days after admission." (PMID 33580165, 2021). "Association with mortality was independent of age, the coexistence of arterial hypertension, the location and extension of the PE, thrombolysis, as well as admission anemia, renal dysfunction, lymphopenia, BNP and CRP." (PMID 33142963, 2020). "Odds were not statistically significant for overweight, high blood pressure, sedentarism, AMI, high serum concentration of triglycerides, homocysteine, or C-reactive protein models." (PMID 31141980, 2019). "In cancer patients, only the CRP correlated with the BNP independent of the age, creatinine level, hypertension, and body mass index." (PMID 28570595, 2017). "In patients with untreated stage I hypertension, daily consumption of 100 g dark chocolate for 15 days did not affect ICAM-1 and CRP." (PMID 27240397, 2016). "Survivors compared to non-survivors were more likely to have hypertension; higher mean MMSE scores; higher serum albumin levels; and lower mean serum levels of CRP, IL-6, and ET-1." (PMID 26289439, 2015). "Hirota reported that casein hydrolysate containing Val-Pro-Pro and Ile-Pro-Pro supplementation in subjects with mild hypertension significantly reduced circulating TNF-α levels, although no alteration in circulating CRP level was found." (PMID 25671415, 2015). "The main outcomes evaluated after implementing these dietary models are as follows: CVD-related death; the development of specific CVDs, such as myocardial infarction and hypertension; or biochemical parameters related to CVDs, i.e., non-HDL cholesterol, C-reactive protein (CPR) and homocysteine." (PMID 38794710, 2024). "Between the two groups,there were statistically significant differences in age, hypertension, previous strokes, WBC, neutrophil, monocyte, eosinophil, albumin, BUN, Cr, free IL-2, IgA, IgG, CRP, C4 (p < 0.05), and the other factors were not significantly different (p > 0.05)." (PMID 38887608, 2024). "However, age, gender, hypertension, anti-AQP4 antibody status, blood monocytes, lymphocyte count, TC, TG, LDL, ESR, CRP, and lymphocyte to HDL ratio were not significantly correlated with the initial EDSS score." (PMID 34777231, 2021).